CBLN2 (cerebellin 2 precursor)
Description:
Acts as a synaptic organizer in specific subsets of neurons in the brain. Essential for long-term maintenance but not establishment of excitatory synapses. Functions as part of a trans-synaptic complex by binding to postsynaptic GRID1 and presynaptic neurexins. This interaction helps regulate the activity of NMDA and AMPA receptors at hippocampal synapses without affecting synapse formation. NRXN1B-CBLN2-GRID1 complex transduce presynaptic signals into postsynaptic NMDAR response. NRXN3B-CBLN2-GRID1 complex transduce presynaptic signals into postsynaptic AMPAR response.
Tractability: Antibody: UniProt places it where antibodies can reach, with medium confidence; UniProt predicts a signal peptide or a membrane-spanning region; its Gene Ontology location is reachable by antibodies, with medium confidence.
Gene: Protein-coding gene on chromosome 18 (72,534,118 to 72,638,521, reverse strand). Ensembl gene ENSG00000141668.
Subcellular location: Secreted
Subcellular location (Human Protein Atlas): Cytosol; Flagellar centriole; Mid piece; Principal piece; Calyx; Perinuclear theca; Predicted to be secreted
Gene Ontology:
Molecular function: signaling receptor regulator activity
Biological process: trans-synaptic signaling by trans-synaptic complex, modulating synaptic transmission; maintenance of synapse structure; spontaneous synaptic transmission; synapse organization; trans-synaptic signaling, modulating synaptic transmission
Cellular component: synapse; extracellular region; synaptic cleft; trans-synaptic protein complex; glutamatergic synapse
Genetic constraint (gnomAD): Loss-of-function variants: 7 observed, 11.76 expected, observed/expected ratio (o/e) 0.6, 90% interval 0.34 to 1.12. The synonymous counts are far from expectation, so gnomAD's model fits this gene poorly and the ratio says little. Missense variants: 242 observed, 270.69 expected, observed/expected ratio (o/e) 0.89, 90% interval 0.8 to 0.99. Synonymous variants: 149 observed, 112.32 expected, observed/expected ratio (o/e) 1.33, 90% interval 1.16 to 1.52.
Homologues: Orthologues: chimpanzee CBLN2 (100% identical), macaque CBLN2 (99% identical), dog CBLN2 (96% identical), pig CBLN2 (95% identical), rat Cbln2 (95% identical), guinea pig CBLN2 (94% identical), mouse Cbln2 (94% identical), tropical clawed frog cbln2 (77% identical), zebrafish cbln2b (72% identical), zebrafish cbln2a (67% identical). Paralogues in human: CBLN1 (66% identical), CBLN4 (62% identical), CBLN3 (49% identical).
Diseases named in the same sentence as CBLN2 in open-access papers:
CBLN2 is named in the same sentence as 19 diseases in open-access papers, as found by Europe PMC text mining. Sharing a sentence is not in itself a finding about the gene and the disease. The quoted sentences say what the papers report.
pulmonary arterial hypertension (3 papers, 2016 to 2019). Pulmonary arterial hypertension (PAH) is a group of diseases characterized by mean pulmonary artery pressure >20 mmHg and elevated pulmonary arterial resistance leading to right heart failure. "Common variants of CBLN2 are associated with increased risk of pulmonary arterial hypertension." (PMID 30258496, 2018). "In this study, we analyzed 7 PAH-causing genes including BMPR2, ACVRL1, ENG, SMAD9, CAV1, KCNK3, and CBLN2 in 49 CTEPH patients and 17 patients recovered from pulmonary embolism (PE) but without pulmonary hypertension(PH)." (PMID 26820968, 2016).
colorectal cancer (2 papers, 2021 to 2023). A primary or metastatic malignant neoplasm that affects the colon or rectum. "AIMs, rs12916300 and rs12913832, mapped to HERC2 (chr15) and rs694339 in the CBLN2 (chr18) genes were associated with colorectal cancer risk in a European sample." (PMID 36911410, 2023).
injury (1 paper, 2025). Damage inflicted on the body as the direct or indirect result of an external force, with or without disruption of structural continuity. "Beyond direct regulation of Cbln2, SOX11 may influence broader transcriptional programs through interactions with downstream factors such as ATF3 and c-JUN, both of which are well-established contributors to neuropathic pain following nerve injury." (PMID 41162740, 2025).
neuropathic pain (1 paper, 2025). Chronic pain caused by damage to nerve fibers. "As the most common neuropathic pain model, SNL induced upregulation of CBLN2 in L5 DRG of rats (GSE24982)." (PMID 41162740, 2025).
tumor (1 paper, 2021). "CBLN2 and TMEM220 protein expression levels were significantly different in tumor tissues as compared to controls." (PMID 34182539, 2021).
CBLN2 also shares sentences with these, for which no sentence is quoted: cancer (2 papers); autism (1); cervical cancer (1); esophageal small cell carcinoma (1); head and neck cancer (1); obsessive-compulsive disorder (1); ovarian carcinoma (1); prostate carcinoma (1); pulmonary embolism (1); pulmonary hypertension (1); schizophrenia (1); Sepsis (1); Tinnitus (1); Tourette syndrome (1).